CCNB1 (cyclin B1)
Diseases named in the same sentence as CCNB1 in open-access papers (continued):
Sharing a sentence is not in itself a finding about the gene and the disease.
lung cancer (continued). "We report here that BRG1 recruits KDM3A to activate CCNB1 and LTBP2 transcription in lung cancer cells." (PMID 31695026, 2019). "Overexpression of CCNB1 and CCNB2 has been observed in some human cancer samples, and CCNB1 and CCNB2 possess clinical significance in the diagnosis and prognosis of various cancers, such as lung cancer and pancreatic cancer." (PMID 31886163, 2019). "BRG1 depletion or inhibition was paralleled by down-regulation of cyclin B1 (CCNB1) and latent TGF-β binding protein 2 (LTBP2) in lung cancer cells." (PMID 31695026, 2019). "Our results show that 2HF induced apoptosis in both histological types of lung cancer and inhibited proliferation and growth through suppression of CDK4, CCNB1, PIK3CA, AKT and RPS6KB1 (P70S6K) signaling." (PMID 30546837, 2018). "The protein expression of several cyclins including cyclin A2, cyclin B1, cyclin D1, and cyclin E2 was markedly suppressed by GSK-3α knockdown in lung cancer cell lines." (PMID 27049759, 2016). "Therapeutic effect of our synthetic fc-rPEI-Cdots/pooled siRNA (cyclin B1 plus EGFR) and fc-rPEI-Cdots/single siRNA (cyclin B1) nanoagents was examined by measuring viability of lung cancer cells after treatment." (PMID 26880047, 2016). "We showed that 6-OAP up-regulated pH3 and cyclin B1 and down-regulated the tyrosine-15-phosphorylated Cdc2 (pCdc2 (Y15)) in A549 and H1975 cells, indicating that 6-OAP arrests lung cancer cells in an early stage of mitosis." (PMID 26474281, 2015). "A signature of genes including CDC20, CCNB1, CDC2, CDKN3, MAD2L1, PRC1 and RRM2, were prognostic for 5-year survival in over 400 lung cancer cases, and interestingly, CDC20, CDC2, CCNB1 were also highly overexpressed in the aggressive case." (PMID 22905093, 2012). "In addition, we also found that PLK1, CDK1, CCNB1, and CCNB2 were upregulated in lung cancer, liver cancer, and cervix cancer tissues from HPA." (PMID 37007025, 2023). "It was found that TOP2A, CCNB1, CCNA2, CDK1, and TTK might be the critical target genes of lung cancer." (PMID 34616430, 2021). "It would be of great interest to determine whether this BRG1-KDM3A interplay extends beyond the regulation of CCNB1 and LTBP2 transcription and how it contributes to lung cancer oncogenesis in vivo." (PMID 31695026, 2019). "IRF1 is downregulated in lung cancer, IPF and PAH datasets, probably because it represses the expression of genes involved in anti-proliferative response, such as BIRC5/survivin, CCNB1, CCNE1, CDK1, CDK2 and CDK4 and in immune response, such as FOXP3, IL4, ANXA2 and TLR4." (PMID 31867044, 2019). "Furthermore, researchers have found a negative correlation between MEOX1 and CCNB1 mRNA expression in various lung cancer tissues." (PMID 38180753, 2024). "TOP2A, CCNB1, CCNA2, CDK1, and TTK may be the key target genes of lung cancer." (PMID 34616430, 2021). "Consistent with previous reports that CDC2 (CDK1) and cyclinB1 (CCNB1) are crucial to G2/M transition, CVB-D-induced G2/M arrest was confirmed by the decrease in G2/M-transition-related protein CDC2 and cyclin B1 in a dose-dependent manner in all lung cancer cells." (PMID 34072333, 2021). "The treatment of A549 cells with Mito-TEMPO significantly reversed both the ABN-B-induced up-regulation of p21 and the down-regulations of cyclin B1 and CDK1, suggesting that ABN-B could induce cell cycle arrest at the G2/M phase in human lung cancer cells via mitochondrial ROS generation." (PMID 33327489, 2020).
lung cancer (continued). "Furthermore, CCNB1 and CCNA2 were vital in regulating cell cycle progression, while BRCA1 was involved in DNA repair, damage, and chromatin remodeling and DHX15 overexpression has been shown to promote proliferation and tumor metastasis, particularly in lung cancers." (PMID 38233752, 2024). "Therefore, CHEK1, CCNB1, CCNB2, and CDK1 may be helpful prognostic biomarkers for lung cancer." (PMID 36714024, 2023). "In the context of lung cancer, although no studies have directly confirmed a direct interaction between KIF2C and CDK1/CCNB1, research has identified a significant positive correlation in their expression levels." (PMID 41333555, 2025).
gastric cancer (65 papers, 2006 to 2025). A primary or metastatic malignant neoplasm involving the stomach. "The lymph node metastasis of gastric cancer has been associated with overexpression of Cyclin B1, with one study showcasing the role of CDK1 and Cyclin B1 pathways in the loss of p27 and progression of gastric cancer." (PMID 36769170, 2023). "Ten studies reported the association between positive/high expression of cyclin B1 and 5-year OS, of which four were about patients with esophageal cancer, four about gastric cancer and two about colorectal cancer." (PMID 29221213, 2017). "One study reported that cyclin B1 overexpression in gastric cancer tissues was associated with favorable OS, while recent research demonstrated that elevated cyclin B1 expression was correlated with reduced survival." (PMID 27903976, 2017). "In some tumors like gastric cancer and colorectal cancer, overexpression of Cyclin B1 was associated with less aggressive tumour behaviour." (PMID 25849598, 2015). "Studies had shown that CCNB1 were associated with gastric cancer." (PMID 34126961, 2021). "NHE1 promotes cell proliferation in gastric cancer by modulating the G1/S and G2/M cell cycle transitions, while upregulating positive cell cycle regulators like cyclin D1 and cyclin B1 in gastric cancer cells." (PMID 38370477, 2024). "RPRD1B encodes a nuclear protein that binds to Aurora B, regulating cell cycle protein CCNB1 expression, accelerating G2 to S phase transition in gastric cancer cells." (PMID 39062792, 2024). "In gastric cancer cells, PPI inhibited the development of gastric cancer by promoting the conversion of LC3-I to LC3-II and down-regulating cyclin B1, which induces cell cycle arrest in the G2/M phase in the gastric cancer cell line HGC-27." (PMID 38324023, 2024). "In gastric cancer cells, Cyclin B1 expression is mechanistically regulated via the interaction of Aurora B with CREPT/RPRD1B." (PMID 36769170, 2023). "Thirty-two percent of the 61 patients studied exhibited higher levels of Cyclin B1 levels in gastric cancer using immunohistopathological screening." (PMID 36769170, 2023). "Pak1 regulates the mRNA and protein levels of Cyclin B1 for the promotion of progression and metastasis of gastric cancer as its knockdown resulted in the inhibition of the growth of gastric cancer cells and xenograft tumors." (PMID 36769170, 2023). "It plays an important role in gastric cancer progression and development by regulating the expression of cyclin B1 and B2 (CCNB1, CCNB2) and c-MYC." (PMID 37667288, 2023). "The promoter activity and subcellular distribution of Cyclin B1 are regulated via another oncogene product, Pak1, which is overexpressed in gastric cancer." (PMID 36769170, 2023). "The mRNA of CCNB1 (Cyclin B1) was also significantly higher in gastric cancer tissues compared to normal tissues, as evidenced by The Cancer Genome Atlas (TCGA) and Oncomine datasets." (PMID 36769170, 2023). "Kaempferol led to a noticeable decrease in the protein levels of cyclin B1, Cdc25C and Cdk1 in a dose-dependent manner in gastric cancer cells." (PMID 37239974, 2023). "Cyclin B1 levels are also regulated post-transcriptionally via miR-663, which is a micro-RNA contributing to the suppression of the growth of gastric cancer cells." (PMID 36769170, 2023). "In human gastric cancer cells, suppressing the expression of Cdc25C would promote the cyclin B1/CDK1 complex and result in G2/M arrest." (PMID 35628435, 2022). "CCNB1 is widely expressed in a variety of tumors, such as ovarian cancer, liver cancer, and gastric cancer." (PMID 35479514, 2022).
gastric cancer (continued). "Herein, NDUFC1 knockdown induced gastric cancer cells G2/M phase arrest through regulation of cyclin B1/Cdk1 complex." (PMID 34966665, 2021). "Recently, increasing evidence demonstrated that CCNB1 was over-expressed in considerable cancers with poor prognosis, including gastric cancer, esophageal squamous cell carcinoma, non-small cell lung cancer and astrocytomas." (PMID 31010415, 2019). "The results of flow cytometry also showed that hnRNPR promoted G2/M transition phase of the cell cycle by upregulation CCNB1, These findings indicated that hnRNPR enhanced the cell proliferation of gastric cancer cells via maintaining CCNB1 stability." (PMID 31527303, 2019). "Mechanistically, we revealed that CREPT/RPRD1B interacted with Aurora B to regulate the expression of Cyclin B1 in gastric cancer cells." (PMID 30518842, 2018). "In this study, we provided evidence that CREPT regulated the G2/M transition by up-regulating Cyclin B1 expression in gastric cancer cells." (PMID 30518842, 2018). "We believe that Aurora B-driven CREPT phosphorylation is critical for the Cyclin B1 expression in gastric cancers." (PMID 30518842, 2018). "The overexpression of CCNB1 and TPX2 have been demonstrated to be associated with poor survival in Gc." (PMID 30174615, 2018). "Western blotting analysis also indicated that B19 dose-dependently inhibited the expression of cell cycle-related proteins such as MDM-2, Cyclin B1 and Cdc2 in human gastric cancer cells." (PMID 26919094, 2016). "So far, increased expression of Cyclin B1 has been reported in breast, prostate, esophageal, lung, colon, and gastric cancers." (PMID 25962181, 2015). "Luteolin has been reported to reduce the levels of the CDC25c, CDC2, and cyclin B1 proteins and induces G2/M phase arrest in human gastric cancer cell lines." (PMID 22269172, 2012). "Our data suggest that the inhibition effect of FKB on gastric cancer cell growth may be related to the regulation of cell cycle-related proteins including cyclin A, cyclin B1, Cdc2, and Cdc25C." (PMID 35879950, 2022). "However, the detailed mechanism of Cyclin B1 regulation in gastric cancers remains to be elucidated." (PMID 30518842, 2018). "All the data indicate that CREPT regulates the transcription of Cyclin B1 in gastric cancers." (PMID 30518842, 2018). "Moreover, our western-blot data also showed that LY294002 pretreatment restored osthole induced down-regulation of cyclin B1 and cdc2 in human gastric cancer cells." (PMID 29590128, 2018). "However, other studies revealed that overexpression of cyclin B1 was correlated with favorable outcome of patients with gastric cancer and colorectal cancer." (PMID 27903976, 2017). "Likewise, we also estimated the correlation between cyclin B1 expression and 5-year OS of esophageal carcinoma (EC), gastric carcinoma (GC) and colorectal carcinoma (CRC) by subgroup analysis." (PMID 29221213, 2017). "The highest frequency was cyclin B1 (26.8%) in gastric cancer." (PMID 24822225, 2014). "However, some genes (CHEK1, CDKN1A, CDKN2A, CCNB1, etc.)from the B-terms of the close discovery were cell cycle regulators, suggesting that anandamide might be related to cell cycle in gastric cancer." (PMID 24949851, 2014). "Inhibition of CCNB1 suppresses tumor growth and triggers cell cycle disruption as well as apoptotic death in CRC and gastric cancer." (PMID 41614789, 2025). "Inhibiting CCNB1 expression in cancer cells inhibited cancer cell proliferation and induced cell cycle arrest and apoptosis in CRC and gastric cancer." (PMID 37504265, 2023). "Oridonin is a natural compound extracted from Rabdosia rubescens and in gastric cancer cells (SGC-7901); it blocks the cells at the G2/M phase, reducing both Cyclin B1 and CDK1 levels." (PMID 36769170, 2023).
gastric cancer (continued). "The same study reported that the inhibitor treatment causes a reduction of COX-2, p-ERK, and p-Akt, implicating the Cyclin B1/CDK1 axis and its involvement in other signaling pathways regulating the growth of gastric cancer cells." (PMID 36769170, 2023). "Among natural compounds, flavonoids extracted from Citrus aurantium target Cyclin B1 and CDK1 to induce apoptosis in gastric cancer cells, and have been shown to be potential chemoprevention agents." (PMID 36769170, 2023). "Luteolin (peak 22) has been reported to inhibit the growth of gastric cancer cells (AGS), leading to detention at the G2/M phase by reducing the protein levels of Cdc2, Cyclin B1 and Cdc25." (PMID 36615543, 2023). "Harmaline, an alkaloid, induced G2/M-phase arrest by upregulating cyclin B1 and p-Cdk1 expression in SGC-7901 gastric cancer cells." (PMID 35056723, 2022). "The most shared rewiring hubs are BUB1B (brain, lung-adeno, kidney-clear, kidney-papillary and stomach cancer), CYP11A1 (bladder, brain, kidney-clear and uterus cancer) and CCNB1 (brain, kidney-papillary, lung-adeno and lung-squamous cancer)." (PMID 31396397, 2019). "We show that CA10 treatment reduces the expression of CDC2, Cyclin B1 and MDM2 confirming G2/M cycle arrest in gastric cancer cells." (PMID 29254150, 2017). "In consistent with above statement, CA10 treatment reduced the protein expression of CDC2, Cyclin B1 and MDM2, this further emphasizes that CA10 can inhibit the aggressive potential of gastric cancer cells through G2/M cycle arrest." (PMID 29254150, 2017). "ISL1 serves as a novel regulator for the expression of CCNB1, CCNB2 and C-MYC, which plays significant roles in gastric cancer progression and development." (PMID 27835911, 2016). "In particular, flavonoids isolated from Citrus aurantium were shown to inhibit the growth of human gastric cancer cells, by suppressing the proteins CCNB1 (cyclin B1) and CDK1 which control cell cycle progression; the corresponding genes CCNB1 and CDK1 were found to be upregulated in stomach cancer." (PMID 34422220, 2021). "Moreover, an up-regulated expression of p21 and p27 proteins, as well as down-regulated expression of cyclin-A and cyclin-B1, was observed after MGN treatment in gastric cancer cells, contributing to the S/G2 cell cycle arrest." (PMID 33182753, 2020). "A previous study showed that DADS, but not DATS, treatment induced downregulation of cyclin B1 in human gastric cancers and esophageal squamous carcinoma cells." (PMID 28680385, 2017). "In esophageal cancer, gastric cancer, lymph node-negative breast cancer and non-small cell lung cancer, overexpression of Cyclin B1 have been found to be an useful prognostic parameter." (PMID 25849598, 2015). "Abnormal expression of Cyclin B1 and/or CDK1 has been reported in several types of tumors, such as epithelial ovarian cancer, non-small-cell lung cancer, tongue cancer, breast cancer, gastric cancer and colorectal cancer." (PMID 25849598, 2015). "Menadione has been known as an oxidative damage-inducing agent and has been studied in gastric cancer cell lines, where it resulted in proteasome-mediated degradation of Cyclin B1 and CDK1 without reducing the mRNA levels of these genes, with an overall cell cycle arrest in the G2-M phase." (PMID 36769170, 2023). "Silbinin extracted from milk thistle is a known flavonolignan compound, and in the gastric cancer cell line (MGC-803), it negatively influenced the STAT3 pathway to activate caspase 3 and caspase 9 activities to induce apoptosis with a negative impact on survival, Cyclin B1, and CDK1." (PMID 36769170, 2023).
gastric cancer (continued). "Western blot demonstrated that neither expression of Cyclin D1 nor Cyclin B1 were influenced by ectopic expression of RPL15, indicating there might be other molecules mediating the promoting effect of RPL15 on cell proliferation of gastric cancer." (PMID 16608517, 2006).